SNORD116-27 (small nucleolar RNA, C/D box 116-27)
Synonyms: HBII-85-27
Gene: Small nucleolar RNA gene on chromosome 15 (25,101,575 to 25,101,666, forward strand). Ensembl gene ENSG00000251896.
Gene Ontology:
Biological process: RNA processing
Cellular component: nucleolus
Homologues: Orthologues: chimpanzee SNORD116 (100% identical), macaque SNORD116 (99% identical), mouse Gm22373 (53% identical), rat LOC120100337 (48% identical). Paralogues in human: SNORD116-25 (89% identical), SNORD116-26 (86% identical), SNORD116-30 (75% identical), SNORD116-29 (74% identical), SNORD116-28 (73% identical), SNORD116-20 (70% identical), SNORD116-14 (68% identical), SNORD116-15 (68% identical), SNORD116-17 (68% identical), SNORD116-19 (68% identical), SNORD116-21 (68% identical), SNORD116-22 (68% identical), and 19 more.